CD4 (CD4 molecule)
Diseases named in the same sentence as CD4 in open-access papers (continued):
Sharing a sentence is not in itself a finding about the gene and the disease.
T-cell lymphoma (continued). "To further confirm the binding specificity of the tribody 53G for LAG-3, we investigated also its binding on HuT 78 cell line, which is derived from CD4+ human T cell lymphoma and expresses high levels of LAG-3 receptor, but low or absent levels of PD-1 and PD-L1." (PMID 36071464, 2022). "In mice studies, T-cell PTEN deletions have resulted in the development of CD4+ T-cell lymphomas." (PMID 32373524, 2020). "Therefore, targeting of malignant CD4+ T cells in these T cell lymphomas by an anti-CD4 CAR T cell therapy is considered an option." (PMID 32679920, 2020). "On the other hand, Pten deletion did not cause the development of T-cell lymphomas in either CD4+ helper T-cells or peripheral T-cells." (PMID 31064074, 2019). "However, 10 months postadmission, CD4+ T-cell lymphoma, which can produce IL-5, was detected in the nasopharynx and oropharynx." (PMID 32280790, 2019). "Interestingly this miRNA was recently shown to be significantly downregulated in patients affected by Sézary Syndrome, an aggressive CD4+ T-cell lymphoma." (PMID 29231896, 2017). "Furthermore, PD-L1 expression results in immune suppression thus can be used as a marker for CD4+ T cell lymphoma." (PMID 27894330, 2016). "Thus, consistent with heterozygous mutations of Dnmt3a found in human T cell malignancies, Dnmt3a is a haploinsufficient tumor suppressor gene in the prevention of mouse mature CD8+CD4- T cell lymphomas." (PMID 27690235, 2016). "Finally a proliferative phase around 28 dpi is characterized by formation of visceral tumours that originate from CD4+ T cells lymphoma." (PMID 27894330, 2016). "Of interest, we noticed and described for the first time 6 cases of intestinal T-cell lymphomas characterized by their predilection for small intestine involvement, predominance of small to medium-sized tumor cells, a CD4+, CD56+, EBER+ T-cell phenotype and importantly, relatively favorable outcome." (PMID 27564014, 2016). "CD4-positivity is the major immunohistochemical marker of primary CNS T-cell lymphoma, although other markers may include positive staining for pan T antigens (including CD3 and CD5)." (PMID 25789045, 2015). "Finally, double transgenic mice expressing both Tax and HBZ under the control of the CD4 promoter have increased memory T cells and FoxP3+ Treg cells leading to the development of T cell lymphoma and skin lesions." (PMID 26690200, 2015). "In the MYC p19ARF−/− mice, four tumors analyzed were also CD4+/CD8+ T-cell lymphoma." (PMID 25784651, 2015). "Our MYC mice historically all develop CD4+/CD8+ T-cell lymphoma." (PMID 25784651, 2015). "SupT1 is a non-Hodgkin's T cell lymphoma line that expresses high levels of surface CD4." (PMID 26495836, 2015). "The etiology of indolent small intestinal CD4+ T-cell lymphomas is unclear." (PMID 23861889, 2013). "Our results and the published reports indicate low morbidity and long survival of patients with indolent small intestinal CD4+ T-cell lymphomas, often exceeding a decade in contrast to the median overall survival of 10 and 7 months, respectively, for patients with EATL types I and II." (PMID 23861889, 2013). "Hence, we evaluated the pathologic, genomic and clinical characteristics of three cases of indolent CD4+ T cell lymphomas, primarily involving the small intestine." (PMID 23861889, 2013). "Here, we report a successful case of therapy-refractory cutaneous CD4+ T-cell lymphoma treated with helical irradiation of the total skin (HITS) and dose painting technique to overcome the surface dose in homogeneity of conventional radiotherapy and to spare the previous irradiating area." (PMID 24175298, 2013). "TCF8 mutant mice frequently develop invasive CD4+ T cell lymphomas in vivo." (PMID 23060864, 2012). "Furthermore, transgenic expression of HBZ in CD4+ T cells induces T cell lymphomas and systemic inflammation in mice." (PMID 23060864, 2012).
T-cell lymphoma (continued). "Coexpression of MYC and BCL-XL or BCL-2 strongly favored tumor development towards myeloid leukemia, whereas coexpression of MYC and FLIPL did not affect the distribution of myeloid versus lymphoid tumor cells, but changed the ratio between single CD4+ and double positive CD4+CD8+ T-cell lymphomas." (PMID 22393362, 2012). "However, a change in distribution of immature CD4+CD8+ versus mature CD4+ T-cell lymphoma was observed in MYC/FLIPL mice, possibly as a result of increased survival of the CD4+ population, but this did not significantly affect the outcome of the disease." (PMID 22393362, 2012). "Thus, the T-cell lymphomas in HBZ-Tg mice phenotypically resemble ATL, suggesting that HBZ promotes proliferation of CD4+ T cells and predisposes expressing cells to transform in due course." (PMID 21347344, 2011). "Similarly, CD4-positive T-CUS, although rarely observed, may pose a diagnostic challenge due to their similarity to certain T-cell lymphoma types." (PMID 39796028, 2024). "To reveal whether STAT4 downregulation in mature T-cell neoplasms is a phenomenon specific to T-PLL, we re-analyzed published gene expression profiling (GEP) array data from different entities of mature T-cell lymphomas (TCL) compared to either pooled CD4+ or CD8+ T cells." (PMID 37173993, 2023). "Additionally, MET expression is able to activate CD4+ T cells and can induce tumor cell killing in natural killer/T-cell lymphoma cell lines, in which MET elicits an anti-tumor immune response by increasing the activation of T cells and reducing the synthesis of TGF-beta." (PMID 33437521, 2020). "Indeed, anti-CD4 mAb treatment showed activity in CD4+ T cell lymphomas, without significantly increasing the risk of life-threatening infections." (PMID 29070883, 2017). "Upon differentiation of an HTLV-1 infected CD34+ HPC, the alteration of miRNA levels may favor T-cell differentiation, as recently demonstrated by the exclusive development of CD4+ mature T-cell lymphomas in HU-SCID mice reconstituted with CD34+ HPCs infected ex vivo with HTLV-1." (PMID 20132553, 2010). "Finally, three new variants of cutaneous T-cell lymphoma (CTCL) were introduced, and these are primary cutaneous aggressive epidermotropic CD8+ cytotoxic T-cell lymphoma, primary cutaneous gamma-delta T cell lymphoma and primary cutaneous small/medium CD4+ T-cell lymphoma." (PMID 21234357, 2010). "HeLa cells, primary CD4+ T cells isolated from two individual donors, and the CD4+/CD8- T cell lymphoma Jurkat cell line were infected with the VSV-G-pseudotyped HIV-1-EGFP in a time-course manner." (PMID 39630854, 2024). "A recent study has also proposed the inclusion of TRBC1 in a panel for T-cell lymphoma screening, including CD45, CD4, CD2, CD5, TCRγδ, CD7, CD3 and TRBC1." (PMID 40151427, 2024). "The most represented aberrancies in B-cell lymphoma were MHCII- (9/17, 53%), CD3+/CD21+ (7/17, 41%), CD34+ (4/17, 24%), CD79a- (4/17, 24%), while CD3+/CD21+ (5/8, 63%), CD4-/CD8- (4/8, 50%), CD45- (4/8, 50%), CD5- (4/8, 50%) were expressed in T-cell lymphoma." (PMID 37908841, 2023). "Meanwhile, in T-cell lymphoma, CD3+/CD21+ (63%), CD4-/CD8-(50%), CD5- (50%), and CD45- (50%) were the most common." (PMID 37908841, 2023). "Four tumors originating in irradiated S82A mice were examined and found to have CD3+ and CD8+ or CD4+/CD8+ (double positive, DP) T cell markers, consistent with immature T-cell lymphomas." (PMID 37145994, 2023). "This tumor is a CD30+ T-cell lymphoma that is usually positive for CD2 and CD4 with variable expression of CD5, CD7, and CD8 but it is negative for EBER." (PMID 37958219, 2023). "Two patients with TFH+ or EBV+ CD4+ CD30+ large cell peripheral T-cell lymphoma, one with CD8+ systemic anaplastic large cell lymphoma, and two with systemic EBV+ CD8+ T-cell lymphoma of childhood showed a lethal progressive clinical course within 13 months." (PMID 36544095, 2022).
T-cell lymphoma (continued). "As prior studies have suggested that GATA-3 expressing mature T-cell lymphomas may be ontologically derived from Th2 cells, we examined the relationship between the GATA-3 target genes we identified and those associated with differentiated subsets of CD4 + T cells." (PMID 36329027, 2022). "There is one open phase I trial using CD4-directed CAR T-cells for CD4+ T-ALL and T-cell lymphoma (NCT03829540)." (PMID 35955734, 2022). "TOX is a diagnostic marker for cutaneous T-cell lymphomas (CTCL) and is overexpressed in affected CD4+ cells Retinoids have been successfully used in the therapy of CTLC for over 30 years and are still being used in T-cell lymphoma therapy." (PMID 33653267, 2021). "Flow cytometrically, abdominal fluid lymphocytes were highly positive for CD4, CD5, CD18, CD45, and MHC II, consistent with T cell lymphoma." (PMID 33602231, 2021). "T cell defects, T cell lymphomas, and increased incidence of CD3+, CD4+, CD8+, CD3+HLA-DR+, CD4+HLA-DR+, and CD8+HLA-DR+ subset of activated T cells have been observed in lung and peripheral blood of patients with GD." (PMID 34884512, 2021). "NHL accounts for 80–85% of lymphoma, including B-cell NHLs (B-NHLs) expressing CD20 or CD19, T-cell NHLs (T-NHLs) expressing CD3, CD4, or CD8, and natural killer (NK)/T-cell NHLs expressing CD56." (PMID 32296035, 2020). "Immunohistologically, extranodal NK/T-cell lymphoma cells show CD3 and CD56 positivity, while CD4, CD8, and T-cell-related antigens are negatively expressed." (PMID 30603836, 2019). "Expression of Itk-Syk via CD4 promoter-driven Cre in transgenic mice leads to peripheral CD4 and/or CD8 SP T-cell lymphoma in mice with tumour cells having an activated T-cell phenotype (CD62loCD44hi; also indicative of an effector memory T cell)." (PMID 27683157, 2016). "Analysis of CAV1 expression using 212097_at probe signal intensity revealed that all mature T-cell lymphoma subtypes analyzed have a higher mean expression of CAV1 (p < 0.001, FDR < 0.001) as compared to healthy CD4+ and CD8+ T-cell controls." (PMID 26566034, 2015). "Further, the long latent period before the onset of T-cell lymphomas in HBZ-Tg mice suggests that additional genetic and/or epigenetic alterations in CD4+ T cells are necessary for the development of T-cell lymphomas in HBZ-Tg mice as well as for ATL." (PMID 21347344, 2011). "Broadly speaking, this strategy can be considered for stage IA mycosis fungoides, primary cutaneous CD4+ small/medium pleomorphic T-cell lymphomas, and subcutaneous panniculitis-like T-cell lymphomas with no symptoms." (PMID 37999132, 2023). "While they are rarely expressed on T cell lymphomas, LAG3 is expressed on CD4+ and CD8+ tumor-infiltrating lymphocytes and could be a druggable target alone or in combination with CD47." (PMID 36429020, 2022). "In the T-cell lymphoma contingent, the less expressed T-cell markers are CD7 and then CD4." (PMID 36428786, 2022). "T cell lymphomas were primarily CD4+, less frequently CD4−CD8− and rarely CD8+ or CD4+CD8+." (PMID 29985390, 2018). "Since MS may express T-cell markers (such as CD43, CD45, CD4, and CD7), immunohistochemical expressions of MPO, lysozyme, and CD68 should be analyzed for their distinction from T-cell lymphomas." (PMID 25805673, 2015). "Prior to this report, systematic genomic evaluation of indolent small intestinal CD4+ T-cell lymphomas was lacking." (PMID 23861889, 2013). "By 5 months post-transplant, two out of eight mice in the KO to KO transplant group had succumbed to tumor pathology, including one case of CD4+ T-cell lymphoma in the thymus and one case of kidney tumor, with no tumors observed in any of the other groups." (PMID 23705069, 2013). "Rare cases of primary, small intestinal CD4+ T-cell lymphomas with indolent behavior have been described, but are not well characterized." (PMID 23861889, 2013).
T-cell lymphoma (continued). "Previous studies of Myc-induced CD4+/CD8+ T–cell lymphoma in the CD2-MYC model in a lpr genetic background showed that deletion of Fas did not accelerate T-cell lymphoma development, although an increased population of CD4+ T-cells was found." (PMID 22393362, 2012). "The CD2, CD3, CD4, CD7 and CD8 are used to determine the T cell lymphoma." (PMID 20062547, 2009). "T cell lymphomas (TCLs) represent a heterogeneous group of malignancies, arising from either innate lymphoid cells, such as natural killer (NK) and gamma-delta (ɣδ) T cells, or from CD8+ and, more commonly, CD4+ T-helper cells of the adaptive immune compartment." (PMID 41295262, 2025). "Likewise, a population of CD4+ T cells was abundant in the PBMC sample from patient 3156 and absent from the other two donor samples; we subsequently learned that patient 3156 had been diagnosed with T-cell lymphoma." (PMID 38466569, 2024). "In case 3, no CD4+/CD8+IFNγ+ SARS-CoV-2-specific T-cells appeared despite VST treatment, which could be explained by the relapse of T-cell lymphoma, causing a long-term immunosuppressive state." (PMID 37414968, 2024). "Since the use of anti-CD4 mAbs showed a reversible depletion of CD4+ cells in T-cell lymphoma patients without inducing immunosuppression, third-generation anti-CD4 CARs (containing 4-1BB and CD28 costimulatory domains) were then developed, demonstrating in vitro and in vivo preclinical efficacy." (PMID 36624522, 2023). "Multiple clinical studies using monoclonal antibody-based therapies such as ibalizumab targeting CD4 have shown that transient ablation of CD4-expressing cells is well-tolerated in patients with T-cell lymphoma without evidence of irreversible immunosuppression or other long-term adverse events." (PMID 29348865, 2017). "Since the cells also exhibit low and intermediate expression of CD4 and TCRδγ, respectively, we could not completely rule out a T-cell lymphoma with aberrant expression of CD11c, although subsequent genomic results further supported HS." (PMID 27639374, 2016). "The cell of origin of indolent small intestinal CD4+ T-cell lymphomas is not known at present." (PMID 23861889, 2013). "However, while the ratio of AML versus T-cell lymphoma was not altered, the incidence of mature CD4+ T-cell lymphoma increased at the expense of immature CD4+/CD8+ T-cell lymphoma in MYC/FLIPL mice." (PMID 22393362, 2012). "This might indicate that overexpression of FLIPL favors differentiation of T-cell lymphoma cells or increases the survival of mature CD4+ T-cell lymphoma cells, but does not change the overall tumor burden." (PMID 22393362, 2012). "Monomorphic epitheliotropic intestinal T-cell lymphoma (MEITL) is a subtype of T-cell lymphoma that typically consists of small to medium-sized lymphoid cells with epitheliotropism and is immunophenotypically positive for CD8 but negative for CD4 and CD30." (PMID 41395560, 2025). "Similar to the initial biopsy, the tumor cells were positive for LCA and CD4; however, they were negative for the other T cell markers, including CD3 and CD7, ruling out the diagnosis of T-cell lymphoma." (PMID 41159020, 2025). "Of the T-cell lymphoma populations, 98 (80%) were CD4-positive, 12 (10%) were CD4/CD8-double-negative, 11 (9%) were CD8-positive and 1 (1%) was CD4/CD8-doublepositive." (PMID 39796028, 2024). "Anaplastic large cell lymphoma is a CD30+ T-cell lymphoma, usually positive for CD2, CD4, and variable expression of CD5, CD7, and CD8 but negative for B-cell markers." (PMID 37958219, 2023). "The patient’s biopsy specimen of a neck lymph node showed CD4+ and CD25+ non-cytotoxic mature T-cell lymphoma." (PMID 35464471, 2022). "We used two NK cell lines, SNK6 and NK92MI, for these studies; SNK6 cells are nasal NK/T cell lymphoma cells, are positive for CD56, and negative for CD3, CD4, CD8, CD19, and TCR." (PMID 33990633, 2021).
T-cell lymphoma (continued). "Below this threshold and as expected from studying patients with no T-cell lymphoma, the EORTC method consistently produced higher Sezary cell counts, even in the absence of clonal CD4-positive T cells detectable by TRBC1." (PMID 33673033, 2021). "In our in vivo analysis we did not detect any defect in T cell maturation at the CD4+/CD8+ double positive to CD4+ and CD8+ single positive transition or any earlier stage, nor did the mice develop any T cell lymphomas as a result of chromosomal anomalies." (PMID 31276497, 2019). "Another preclinical model, the patient derived xenograft (PDX) mouse model for AITL is not mimicking closely the T cell lymphoma since upon transplantation of human AITL biopsies into NSG mice the CD8 T cells and B cells do not engraft anymore and only the CD4 + PD1highneoplastic cells persist." (PMID 39272178, 2024). "Phase I clinical trials (NCT03829540, NCT04219319, NCT04162340) have now been initiated to evaluate the safety and tolerability of anti-CD4 CAR-T cells in T cell malignancies, including T cell leukemia and T cell lymphoma; the outcomes have not yet been reported." (PMID 36059451, 2022).